DCAF8L1 (DDB1 and CUL4 associated factor 8 like 1)
Synonyms: WDR42B
Tractability: No criterion of Open Targets' tractability assessment is met for any kind of drug.
Gene: Protein-coding gene on chromosome X (27,977,992 to 27,981,449, reverse strand). Ensembl gene ENSG00000226372.
Gene Ontology:
Cellular component: Cul4-RING E3 ubiquitin ligase complex
Homologues: Orthologues: chimpanzee DCAF8L1 (98% identical), tropical clawed frog dcaf8 (62% identical), rat AABR07038690.1 (55% identical), mouse Dcaf8l (54% identical), zebrafish dcaf8 (52% identical), Drosophila melanogaster CG8001 (31% identical). Paralogues in human: DCAF8L2 (80% identical), DCAF8 (68% identical), DCAF6 (24% identical), WDTC1 (22% identical), DCAF5 (17% identical).
Diseases named in the same sentence as DCAF8L1 in open-access papers:
DCAF8L1 is named in the same sentence as 13 diseases in open-access papers, as found by Europe PMC text mining. Sharing a sentence is not in itself a finding about the gene and the disease. The quoted sentences say what the papers report.
breast carcinoma (1 paper, 2022). "Consistent with this notion, we found that X-linked gene DCAF8L1 is upregulated in some of the breast cancers; in addition, loss of Xi was also observed in DCAF8L1-overexpressing cell line HCC1954." (PMID 35280675, 2022). "Since BRCA1-deficient breast cancer is sensitive to PARPi33, 48, future exploration using PARPi for the treatment of these cancers with high DCAF8L1 expression will have important implications." (PMID 35280675, 2022). "Collectively, these results indicate that DCAF8L1 is aberrantly expressed in breast cancer cell lines and tissues, suggesting that alteration of DCAF8L1 might be associated with breast cancer progression and development." (PMID 35280675, 2022). "Since DCAF8L1 is an X-linked gene, and many breast cancers display X chromosome misbehavior including X chromosome duplication and loss of XCI, our study may have important implications in understanding the relationship between BRCA1, X chromosome instability and breast tumorigenesis." (PMID 35280675, 2022). "In this study we found DCAF8L1 is expressed in most of the human fibroadenomas and in a small proportion of the breast cancer cell lines (HCC1954 and T47D) and tissues (21% with medium to high expression)." (PMID 35280675, 2022). "This type of high-DCAF8L1 expressing cells was also found in many of the breast cancers, in particular the triple negative breast cancers (40-50%)." (PMID 35280675, 2022). "Based on the fact that DCAF8L1 is overexpressed in many breast cancers, these findings might have important implications in cancer therapy." (PMID 35280675, 2022). "Next, the expression of DCAF8L1 was examined in breast cancer cell lines and tissues." (PMID 35280675, 2022). "Interestingly, strong cytoplasmic DCAF8L1 staining was also observed in a few yet-unidentified type of mammary cells in both normal breast, breast fibroadenomas and breast cancer tissues (probably tissue macrophages or tumor infiltrating lymphocytes, TILs)." (PMID 35280675, 2022). "Aberrant expression of DCAF8L1 was observed in human breast fibroadenoma and breast cancer." (PMID 35280675, 2022). "Here we report the identification of DDB1 and CUL4-associated factor 8-like protein 1(DCAF8L1), a novel DCAF protein which is encoded by an X-linked gene, plays crucial role in targeting BRCA1/BARD1 for proteasomal degradation, and might be involved in the development of breast cancer." (PMID 35280675, 2022). "Immunoblotting showed that DCAF8L1 was expressed mainly in HCC1954 and T47D, two breast cancer cell lines with luminal epithelial characteristics." (PMID 35280675, 2022). "In contrast to fibroadenomas, most of the breast cancers do not express DCAF8L1; Of all the 150 cases of breast invasive ductal carcinoma tissues examined, 98 (65.3%) are negative, and 31 are weak in DCAF8L1 staining; only 8(5.3%) display high expression with nuclear staining of DCAF8L1." (PMID 35280675, 2022).
breast tumor (1 paper, 2022). "Interestingly, the expression of DCAF8L1 is also observed in a few of yet-unidentified cells (seems to be breast tissue macrophages or breast tumor infiltrating lymphocytes, TILs) in both fibroadenomas and invasive breast cancers (arrows)." (PMID 35280675, 2022). "To validate whether the oncogenic potential of DCAF8L1 is important in breast tumor progression, we first examined whether overexpression of DCAF8L1 could promote cell proliferation." (PMID 35280675, 2022).
Fibroadenoma (1 paper, 2022). A benign tumor of the breast characterized by the presence of stromal and epithelial elements. "DCAF8L1 expression is negative in ducts and terminal duct lobular units (TDLUs) of normal breast tissues, and is significantly upregulated in breast fibroadenomas." (PMID 35280675, 2022).
lentivirus infection (1 paper, 2022). Virus diseases caused by the Lentivirus genus. "DCAF8L1 in HCC1954 cells were depleted by shRNA lentivirus infection." (PMID 35280675, 2022).
neuroblastoma (1 paper, 2024). Neuroblastoma (NB) is the most common solid, extracranial childhood tumor. "Studies have shown that CDK5R2 CYP26B1, DCAF8L1, PAGE1, and TRIM36 can be used to construct prognostic models or prognostic biomarker for HCC, rectal cancer, neuroblastoma, etc." (PMID 38649860, 2024).
cancer (2 papers, 2022 to 2024). A tumor composed of atypical neoplastic, often pleomorphic cells that invade other tissues. "In the current study, we found that DCAF8L1 was significantly increased in HCC tissues campare to para-carcinoma tissues and positively associated with tumor aggressiveness, including OS rate, T stage and AFP level." (PMID 38649860, 2024). "Taken together, these findings suggest that DCAF8L1 could promote cancer cell proliferation and regulate mammary stem/progenitor cell development and differentiation, probably through a mechanism dependent on its negative regulation of BRCA1 protein." (PMID 35280675, 2022). "Most HCC tissues exhibited elevated protein levels of CDK5R2, CYP26B1, DCAF8L1, PAGE1, and TRIM36 in comparison to para-carcinoma tissues, as indicated by the results." (PMID 38649860, 2024).
tumor (2 papers, 2022 to 2024). "This analysis identified TRIM36, CYP26B1, PAGE1, CDK5R2, and DCAF8L1 as a molecular signature associated with tumor aggressiveness." (PMID 38649860, 2024). "DCAF8L1 depleted cells or the vector control cells were subcutaneously injected (4 × 106 cells) to mammary fat pad of female SCID mice, tumor latency and growth were recorded." (PMID 35280675, 2022). "Recognizing the critical role of m1A in tumor progression and prognosis, a reliable prognostic signature based on five DEGs characterizing autophagy among the m1A modification patterns (CDK5R2, CYP26B1, DCAF8L1, PAGE1, and TRIM36) was initially established." (PMID 38649860, 2024). "Forced expression of DCAF8L1 in MCF10F or HCC1954 cells promotes cell proliferation; next, we investigated whether depletion of DCAF8L1 in HCC1954 cells could affect tumor growth in vivo." (PMID 35280675, 2022).
DCAF8L1 also shares sentences with these, for which no sentence is quoted: benign neoplasm (1 paper); breast (1); invasive breast carcinoma (1); invasive ductal carcinoma (1); rectal cancer (1); triple-negative breast carcinoma (1).